MIR492 (microRNA 492)
Synonyms: hsa-mir-492; MIRN492
Gene: MicroRNA gene on chromosome 12 (94,834,398 to 94,834,513, forward strand). Ensembl gene ENSG00000283998.
Gene Ontology:
Biological process: miRNA-mediated post-transcriptional gene silencing
Homologues: Orthologues: chimpanzee ptr-mir-492 (98% identical).